NLRP3 (NLR family pyrin domain containing 3)
Diseases named in the same sentence as NLRP3 in open-access papers (continued):
Sharing a sentence is not in itself a finding about the gene and the disease.
infection (continued). "Previous studies have demonstrated that NLRP3 expression is inducible following infection and implicate this as the rate limiting step in inflammasome activation but little is known about the regulation of NLRC4 expression." (PMID 22174673, 2011). "The toxins nigericin and maitotoxin, as well as infection with Staphylococcus aureus also induce NLRP3-dependent IL-1β release." (PMID 22019906, 2011). "We show that infection with Candida albicans leads to up-regulation of NLRP3 and NLRC4 expression in the oral mucosa and this induction is impaired in both NLRP3 and NLRC4 deficient mice." (PMID 22174673, 2011). "IL-1β cleavage is a hallmark of inflammasome activation, and we observed significant Pycard, Nlrp3, and Casp-1-dependent inflammasome activation during in vitro infection of cultured cells." (PMID 20808838, 2010). "Induction of the NLRP3 inflammasome was not limited to virulent Mtb H37Rv infection, but also occurred with attenuated Mtb H37Ra." (PMID 20808838, 2010). "We assessed bacterial burden in the lungs of Pycard−/− and Nlrp3−/− mice in two separate infections, with each compared to paired C57BL/6 controls." (PMID 20808838, 2010). "It is possible that early activation of NLRP3 and IL-1β production results in the infiltration of neutrophils and monocytes to the sites of infection where these cells continue to secrete cytokines resulting in a “cytokine storm”." (PMID 19798428, 2009). "Our data support the fact that α-hemolysin can indeed activate the NLRP3 inflammasome, but suggests that this host response is likely to vary depending on the site of infection and types of host inflammatory cells present to combat it." (PMID 19826485, 2009). "Targeting the sG-TLR2 interface could reduce inflammatory damage and viral spread, providing a rationale for CX3C motif-directed interventions and NLRP3 inhibitors during infection." (PMID 41593203, 2026). "Retinal and cortical proteomics reveal bacterial-infection and related NLRP3-inflammasome pathways." (PMID 41571675, 2026). "The NLRP3 inflammasome mediates the maturation of IL-1β and IL-18 primarily in myeloid cells, thereby shaping inflammatory and immunoregulatory responses during infection." (PMID 41753558, 2026). "In models, infection drives Aβ deposition and NLRP3 activation, worsening pathology and cognition." (PMID 41571675, 2026). "Interestingly, NLRP3 was also reported to detect infection by various pathogens, including L. monocytogenes." (PMID 41266655, 2026). "We therefore wanted to establish whether the presence of S. pneumoniae induced phagocytic cell pyroptosis through NLRP3 and used a BV‐2 cell infection model for this purpose." (PMID 39887961, 2025). "Early during infection, some DCs activate the caspase-11 and NLRP3 inflammasomes." (PMID 40530878, 2025). "Furthermore, genes associated with inflammaging (IFNα, IL1β, NLRP3, IL6, IL1R and p16) and myeloid lineage (RUNX1, Fil1, CD150, PU.1 and GM-CSF) genes that were upregulated by Omicron PsV infection were downregulated by NGO treatment." (PMID 40025168, 2025). "Thus, the Nlrp3/Gsdme inflammasome axis governs homeostatic turnover of both neutrophils and macrophages, but during infection, ST exploits this pathway specifically to kill neutrophils." (PMID 41360763, 2025). "Meanwhile, the expression of NLRP3 in macrophages increased significantly after infection." (PMID 41190868, 2025). "NLRP3 inflammasome plays a crucial role in the innate immune response, and activation of the NLRP3 inflammasome occurs in response to infection or cellular injury, wherein the inflammasome components oligomerize and assemble, leading to the activation of procaspase-1 into its active form." (PMID 40851698, 2025). "Since NLRP3 activation generally needs a longer time, the rapid expression of LPS-mediated lncOlfr29 may have an important significance in switching or promoting the activation of NLRP3 by infection to induce inflammation and eliminate bacteria." (PMID 40933997, 2025).
infection (continued). "This suggests that ST exploits Nlrp3 to selectively eliminate neutrophils during infection." (PMID 41360763, 2025). "This study identifies NLRP3 as a central mediator linking immune cell metabolism to defense against infections, providing novel insights into how innate immunity controls pathogenic bacteria and suggesting potential strategies for improving treatment or prevention of severe infections." (PMID 41190868, 2025). "Similar to this, NLRP3 inhibitors may weaken the host’s immune system, especially during an infection, even though they are efficient at preventing inflammasome activation." (PMID 41261343, 2025). "Indeed, the infection prevented the lysosomal damage induced by Aβ or LLOMe and counteracted NLRP3 activation by reducing oxidative stress and preserving lysosomal membrane integrity." (PMID 41162989, 2025). "In conclusion, our findings reveal a novel mechanism by which the ASFV pB169L forms calcium-permeable cation channels to trigger NLRP3 inflammasome activation through disrupting intracellular Ca2+ homeostasis, driving proinflammatory responses during infection." (PMID 41237200, 2025). "Interestingly, DEGs associated with neurodegenerative diseases, such as NLRP3, CSF1, and A2M, exhibit higher expression in the ITA infection group." (PMID 40723822, 2025). "However, the mRNA levels of NLRP3 and caspase-1 were decreased in the Pro10, Pro20, Pro40, Amo20, Pro20 + Amo20, and Bai100 groups compared with the infection group (p < 0.01)." (PMID 40305201, 2025). "Furthermore, SARM participated in the regulation of the inflammatory response through the nod-like receptor pyrin domain 3 (NLRP3) inflammasome signaling pathway during T. gondii in vitro infection." (PMID 40075497, 2025). "Thus, we infected HMEC-1 cells with DENV-2 at an MOI of 5, and then cell lysates were analyzed at different times (12, 24, and 36 h) by Western blotting using specific anti-NLRP3 antibodies to follow the infection with anti NS5." (PMID 41471247, 2025). "For instance, infection with Staphylococcus pseudintermedius activates the NLRP3/HMGB1/ROS/GSDMD signaling axis in corneal epithelial cells, exacerbating apoptosis and leading to the formation of characteristic focal holes, numerous extracellular bubbles, and other localized phenomena." (PMID 40688353, 2025). "Cells were fixed and stained with antibodies against Myc and NLRP3 16 hr post infection." (PMID 39998486, 2025). "Similarly, infection with cagA+ strains has been shown to increase the NLRP3 inflammatory response and increase the potential for cancer and cell migration in the stomach by stimulating ROS generation." (PMID 40563885, 2025). "Moreover, we found that the infection of NLRP3 KO macrophages with V. vulnificus led to glycolytic levels comparable to those observed in macrophages treated with PBS." (PMID 41190868, 2025). "As further confirmation, infection of NLRP3-deleted THP-1 cells and BMDMs completely prevented IL-1β secretion, while preserving secretion of the inflammasome-independent cytokine TNFα, highlighting the specificity of the effect for inflammasome-dependent responses." (PMID 40747430, 2025). "Notably, NLRP3 was found to selectively drive IL‐1β secretion in P. aeruginosa‐infected neutrophils, thereby regulating the severity of infection." (PMID 40529614, 2025). "The NLRP3 deletion weakens the IL-1β secretion and the neutrophil recruitment, indicating that regulating the NLRP3 inflammasome pathway may help defend the infection of C. neoformans in patients." (PMID 41017910, 2025). "For instance, in Staphylococcus aureus, alpha-hemolysin activates the NLRP3 inflammasome in human and mouse monocytic cells, leading to the release of pro-inflammatory cytokines and contributing to the inflammatory response during infection." (PMID 40042275, 2025). "The NLRP3 pathway is essential in innate immunity against damage or infection." (PMID 40959087, 2025).
infection (continued). "In the present study, we found that intestinal NLRP3 expression was significantly upregulated after infection in wild-type mice, whereas TRIM67 deletion inhibited this process, resulting in reduced caspase-1 activity and decreased pro-inflammatory cytokine release." (PMID 40572155, 2025). "The protective role of the NLRP3 inflammasome may be attributed to its capacity to modulate host defense in recognizing pathogens, signals, and clearing the infection." (PMID 41149694, 2025). "This includes the relatively low expression or activity of CARD8 and NLR family pyrin domain containing 3 (NLRP3) components, contributing to their non-pathogenic course of infection." (PMID 40573430, 2025). "Cp activates the NLRP3 inflammasome in murine infection models, however, its effect on NLRP3 activation in the AD retina remains unknown." (PMID 40667156, 2025). "Recent studies have demonstrated that infection with G. parasuis serotype 5 triggers an inflammatory response by activating the NLRP3 inflammasome and induces pyroptosis through the cleavage of gasdermin D (GSDMD) and the activation of Caspase-1, thereby amplifying the inflammatory cascade." (PMID 40665414, 2025). "Instead of effectively fighting the infection, excessive NLRP3 activation triggers uncontrolled inflammation, which can be harmful to the host and may even lead to organ failure and death." (PMID 40723899, 2025). "We found that H37Ra infection could only significantly increase NLRP3 mRNA expression in THP-1 cells." (PMID 40092991, 2025). "In a previous study, it was reported that infection by S. japonicum in BALB/c mice led to increased formation of NLRP3 inflammasome in the liver at approximately 6 wpi, with this pathway being directly related to the fibrotic process in the liver triggered during Schistosomiaisis." (PMID 38896633, 2024). "Dampening of pyroptosis via reduction of macrophage transcriptional activities was demonstrated upon L. donovani infection; transcriptional reduction of caspase-1, NLRP3, and other inflammasome-related genes was observed in PBMCs from VL patients and in macrophage-infection in vitro." (PMID 39392429, 2024). "Accordingly, infection or cellular stressors can lead to cell death by the combinatory crosstalk of pyroptotic, apoptotic, and necroptotic molecules (like ZBP1, RIPK1, RIPK3, CASP1, CASP8, and NLRP3, MLKL, and GSMDs) to effectively control pathogenic invasion." (PMID 38590437, 2024). "Thus, unhealthy people with reduced immune response fitness display a dysregulated NLRP3 inflammasome activity, characterized by a steady and persistent inflammatory response, worsening the infection." (PMID 38644450, 2024). "The NLRP3 inflammasome was reported to be activated upon infection with several Leishmania spp., with roles that could be either beneficial or detrimental, depending on the infecting Leishmania spp." (PMID 39250503, 2024). "Results herein show that infection of human cells with the non-pathogenic L. tarentolae interferes with NLRP3 formation." (PMID 38707903, 2024). "The modulation of the NLRP3 inflammasome by E protein varies across different infection stages." (PMID 39711780, 2024). "This may be due to the increased expression of NLRP3, apoptosis-associated speck-like protein (ASC), caspase-1, and GSDMD associated with pyroptosis in the host upon infection." (PMID 39011036, 2024). "Therefore, several studies have been conducted to understand the interaction of NLRP3 inflammasome with Plasmodium during infection." (PMID 38623843, 2024). "The Nlrp3–/– group exhibited elevated Ym1 levels after infection." (PMID 39405117, 2024). "In this study, we first demonstrated that IL-1β was secreted following the PEDV infection of IPEC-J2 cells and then investigated whether IL-1β secretion during the infection process was mediated by the NLRP3 inflammasome." (PMID 39728983, 2024).
infection (continued). "Besides TLRs, S. mansoni infection also induced higher levels of inflammasome involved-molecules as NLRP1, NLRP3 and Caspase-1 in the second week of infection." (PMID 38896633, 2024). "Thus, upon HBx-mediated infection, the activation of the NLRP3 inflammasome was confirmed by a very high secretion of NLRP3-associated proteins such as ASC, IL-1β, and IL-18." (PMID 38674122, 2024). "In addition, PE_PGRS38 decreased NLRP3-dependent IL-1β release and limited pathogen-mediated inflammasome activity during infection." (PMID 38785795, 2024). "Overall, this demonstrates that CDT contributes to cecal edema and weight loss 2 days post R20291 infection through a mechanism that is independent of the NLRP3 inflammasome." (PMID 39298531, 2024). "Administration of the NLRP3 inhibitor MCC950 at days 1 and 3 after influenza A virus (IAV) infection led to hyper-susceptibility to lethality, whereas treatment on days 3 and 5 post-infection protected mice against IAV-induced disease." (PMID 38662771, 2024). "Furthermore, P1/7 induced NLRP3 inflammasome activation with increased protein expression of NLRP3 and caspase-1 at 9 h post-infection (hpi), leading to the production of inflammatory cytokines, including IL-1β and IL-6." (PMID 39334337, 2024). "Moreover, CV-A16 and CV-A10 infections triggered NLRP3-mediated pyroptosis and promoted the release of inflammatory cytokines." (PMID 38705479, 2024). "The data from comparing two strains in the mouse infection model suggest that CDT contributes to weight loss on the second day of the infection in the mouse infection model and that the contribution is independent of the NLRP3 inflammasome response." (PMID 39298531, 2024). "Conversely, in the later phases of infection, when inflammasomes are triggered by endotoxins, DAMPs, or other viral factors, the E protein engages with viral RNA, potentially fostering the activation of NLRP3 inflammasomes." (PMID 38399989, 2024). "Thus, it is conceivable that in NFKB1 variant carriers, the combined excessive activation of the NLRP3 inflammasome and IFN-I pathways triggered by trauma or minor infection predispose patients to life-threatening inflammatory responses and tissue necrosis." (PMID 38593810, 2024). "NLRP3 plays a crucial role in the immune system, and blocking its activity may also interfere with the body’s ability to fight infections and heal wounds." (PMID 38892264, 2024). "Whereas circulating IL-18 levels were low and showed a decreasing trend without difference between WT and NLRP3−/− mice, levels of IL-1β progressively increased in T. crassiceps-infected WT mice reaching a significant increase in week 8 of infection as compared to NLRP3−/− mice." (PMID 38842647, 2024). "This implies that NLRP3 signaling is protective during the infection." (PMID 39298531, 2024). "Likewise, NLRP3−/− mice were more resistant to Schistosoma mansoni experimental infection as gauged by the presence of smaller liver granulomas than those found in WT animals." (PMID 38842647, 2024). "Additionally, infection with Herpes simplex virus (HSV) also instigates the creation of NLRP3 inflammasomes and consequent IL-1β production in human TH-1 cells, fibroblasts, and melanoma cells." (PMID 38590522, 2024). "Interestingly, mitogen-activated MLN cells showed a steady increased IL-15 levels starting on week 4 of infection in NLRP3−/− mice, whereas spleen levels were higher only at the chronic stage of infection." (PMID 38842647, 2024). "Here, we explored the role of nucleotide-binding oligomerization domain pyrin-containing protein 3 (NLRP3) in Taenia crassiceps experimental infection, which requires immune polarization into a Th2-type profile and peritoneal influx of suppressive macrophages for successful colonization." (PMID 38842647, 2024).
infection (continued). "Thus, in this study, we primarily focused on the mechanism investigation about the role of NLRP3-dependent pyroptosis in inflammatory response and viral replication during CV-A16 and CV-A10 infections." (PMID 38705479, 2024). "However, significant differences in the expression of the NLRP3 were detected (p < 0.05) for the mixed infection in comparison with the A. caviae single infection." (PMID 38721607, 2024). "Furthermore, the expression of NLRP3 was downregulated (2.6-fold reduction, p = 0.021 and 1.7-fold reduction, p = 0.028, during GI.1 and GI.2 infection) compared to healthy rabbits." (PMID 39273479, 2024). "In the present study, we found that infection with GoAstV activated the NLRP3 pathway, and the mRNA expression levels of NLRP3, cleaved caspase-1 and IL-1β were significantly upregulated in the infection group at 24 hpi and 48 hpi compared to those in the control group." (PMID 39502173, 2024). "Initially, it may suppress the host NLRP3 inflammasome response to viral RNA but might enhance the NLRP3 inflammasome response in later infection stages." (PMID 39711780, 2024). "•The study confirmed that NLRP3-dependent pyroptosis might be an important contributing factor for inducing exacerbated inflammation during CV-A16 and CV-A10 infections." (PMID 38705479, 2024). "Therefore, to elucidate the mechanism of NLRP3 inflammasome activation in prion-infected cells after IAV/WSN infection, we measured ROS levels in N2aC24 and N2aC24L1-3 cells after IAV/WSN infection." (PMID 39194237, 2024). "To investigate the contribution of type I IFN signalling to inflammasome activation by A. baumannii, we inoculated WT and Ifnar−/− BMDMs with A. baumannii 1605 and measured Nlrp3 and Caspase-11 transcript levels and pro-inflammatory cytokine levels up to 12 h post infection." (PMID 39533032, 2024). "In addition, activation of NLRP3 can benefit the parasite by reducing both T cell activation and the humoral response, resulting in worsening infection and poorer prognoses." (PMID 38623843, 2024). "In a study carried out with L. amazonensis in murine macrophages, it was demonstrated that Gasdermin D is activated in the initial stages of infection (2 h), which leads to transient cell permeabilization and potassium efflux, promoting the activation of the NLRP3 inflammasome." (PMID 38743668, 2024). "Furthermore, Echo11 can activate the assembly of the NLRP3 inflammasome, leading to the production of IL-1β, which facilitates viral invasion of the brain and subsequent infection of neural cells." (PMID 39767680, 2024). "Additionally, researchers manifested the excessive expression of miR-223 (indicating its anti-inflammatory role in infection with this virus) by inhibiting the expression of the NLRP3 inflammasome gene." (PMID 39273479, 2024). "On day 3 after infection with the influenza A virus, Nlrp3−/− mice displayed localized necrotic bronchiolar epithelial cells and bronchiole blockage by fibrin, neutrophils, macrophages, and necrotic cells, while bronchioles in WT mice remained largely unaffected." (PMID 37376638, 2023). "Next, we performed H. pylori SS1 infection studies in WT, Nlrp3−/−, Pycard−/−, and Casp1−/− mice." (PMID 37365163, 2023). "The NLRP3 inflammasome is involved in the induction of pyroptosis during pathogen infection." (PMID 37457695, 2023). "Kesavardhana and colleagues assessed the antiviral function of DDX3X during IvA infection and reported that the host protein DDX3X in interplay with NLRP3 inflammasome plays a crucial role in organizing a multifaceted antiviral innate response during IvA infection." (PMID 37773712, 2023). "In vitro infection assay also showed SARS-CoV-2 engaged the NLRP3 inflammasome in human monocytes." (PMID 36703213, 2023). "Sh‐MIOX suppressed NLRP3 protein expression in infection‐induced mice with cardiac dysfunction." (PMID 37249295, 2023).